HTRA1 (HtrA serine peptidase 1)
Diseases named in the same sentence as HTRA1 in open-access papers (continued):
Sharing a sentence is not in itself a finding about the gene and the disease.
geographic atrophy (13 papers, 2008 to 2025). "CFH, ARMS2/HTRA1 and C3 genes have been reported to increase the risk of progression from intermediate drusen to large drusen and from large drusen to geographic atrophy and neovascularization." (PMID 25893111, 2015). "The protease HTRA1 is a genetic risk factor for geographic atrophy." (PMID 36064790, 2022). "Interestingly, the ARMS2/HTRA1 locus was significantly more associated to neovascular disease as compared to geographic atrophy." (PMID 31934346, 2020). "The allelic association test for rs11200638 on the promoter of HTRA1 yielded p-values less than 10−10 for geographic atrophy, less than 10−16 for neovascularization, and less than 10−19 for the pooled phenotypes (with an odds ration [OR] of 3.973; 95% confidence interval [CI] 2.928, 5.390)." (PMID 18682806, 2008). "Clinical trials targeting proteins encoded by the AMD-associated genomic loci C3, CFB, CFI, CFH, and ARMS2/HTRA1 are currently ongoing, and a phase III clinical trial for C3 inhibition recently showed a modest reduction of lesion growth in geographic atrophy." (PMID 36108770, 2022). "Anti-HtrA1 antibodies are already under investigation for management of geographic atrophy, though it remains to be seen if this class of drugs also have utility in the treatment of PCV." (PMID 34262165, 2022). "Analysis of HtrA1-mediated cleavage of Dickkopf-related protein 3 in the aqueous humor of patients with geographic atrophy provided evidence of anti-HtrA1 Fab activity and information on duration of activity in a phase 1 study." (PMID 32345717, 2020). "Our data confirm the association between advanced AMD (both geographic atrophy and CNV) and the 10q26 SNPs rs11200638 (HTRA1 promoter) and rs10490924 (LOC387715/ARMS2 A69S), independent of the CFH Y402H polymorphism." (PMID 18682806, 2008). "Recent studies in the literature demonstrate the potential strategic importance of other antibodies, such as anti-HtrA1, in the therapy of AMD geographic atrophy." (PMID 35155457, 2021). "Genes with common risk alleles associated with geographic atrophy and neovascular AMD were upregulated in geographic atrophy RPE cells, including CFH, HTRA1, EFEMP1, and APOE, which provide further evidence of their involvement in the pathogenesis of geographic atrophy." (PMID 35882847, 2022). "We genotyped three SNPs, rs1061170 (exon 9, CFH), rs11200638 (HTRA1 promoter, −512 bp), and rs10490924 (6.6 kb upstream of HTRA1 in LOC387715/ARMS2) in 333 cases with advanced AMD (choroidal neovascularization [CNV] and geographic atrophy) and 171 age-matched examined controls." (PMID 18682806, 2008).
Arthritis (11 papers, 2013 to 2024). Inflammation of a joint. "HtrA1 hyperactivity contributes to arthritis, while single-nucleotide polymorphisms in the HtrA1 promoter have been associated with increased risk of AMD." (PMID 25506911, 2014). "Several studies have found that LPS can aggravate arthritis symptoms by stimulating the secretion of HTRA1 by macrophages in the joints and bones of mice." (PMID 36903482, 2023). "HTRA1 is a critical mediator in many cellular processes and plays a role in the pathogenesis of arthritis and IVD degeneration." (PMID 31867863, 2020). "In arthritis, synovial fibroblasts identified as a major source of HtrA1 degrading cartilage matrix, such as fibronectin and aggrecan, which are abundant in keloid lesions." (PMID 29695130, 2018). "In arthritis, synovial fibroblasts produce abundant HtrA1, and HtrA1 digests cartilage ECM, including fibronectin, collagens, and proteoglycans." (PMID 29695130, 2018). "Expression of HtrA1 is also increased in experimental arthritis and may be involved in this condition." (PMID 35371018, 2022). "HtrA1 is closely concerned with normal osteogenesis and in pathogenesis of arthritis." (PMID 29695130, 2018). "Previous studies suggested that HtrA1 stimulates arthritis by digesting the ECM." (PMID 29695130, 2018). "Mammalian HtrA (high temperature requirement factor A) proteases, comprising 4 multi-domain members HtrA1-4, play important roles in a number of normal cellular processes as well as pathological conditions such as cancer, arthritis, neurodegenerative diseases and pregnancy disorders." (PMID 25248123, 2014). "HTRA1 protein is involved in the occurrence and development of many diseases, including AMD, cerebrovascular disease, arthritis, and so on." (PMID 36903482, 2023). "The expression of HTRA1 is increased in arthritis and IVD degeneration, suggesting that HTRA1 protein is attributed to cartilage degeneration and disease progression." (PMID 31867863, 2020).
ischemic stroke (11 papers, 2021 to 2025). A stroke disorder caused by obstruction of blood flow to the brain, due to thrombotic (local blood clot formation) or embolic (due to a blood clot or other material traveling from another site) event. "This expands recent descriptions of loss-of-function mechanisms for HTRA1 associations with ischemic stroke and coronary artery disease risk." (PMID 41266628, 2025). "In the present study, we reported two HTRA1-CSVD patients with ischemic stroke at a young age, with two unique nonsense mutations: c.1096G >T (p.E366X) and c.151G>T (p.E51X)." (PMID 36619910, 2022). "NOTCH3 and HTRA1 variant carriers were associated with the same ischemic stroke risk as belonging to the upper 0.1% and 0.2% of the population, respectively." (PMID 36300346, 2022). "Patients with ischemic stroke at a young age need particular attention due to the high likelihood of being a carrier of HTRA1 mutations." (PMID 36619910, 2022). "This analysis was limited to NOTCH3 and HTRA1 because significant associations with ischemic stroke had only been found for these variants." (PMID 36300346, 2022). "We demonstrated that NOTCH3 and HTRA1 variants were associated with increased risk of ischemic stroke and vascular dementia." (PMID 36300346, 2022). "Another study also highlighted the central role of HTRA1 in coronary artery disease, discovering that a common causal variant (rs2672592) regulates circulating HTRA1 mRNA and protein levels, increasing the risk of ischemic stroke, small vessel stroke, and coronary artery disease." (PMID 40406620, 2025). "This increase in risk is primarily via ischemic stroke for NOTCH3 and HTRA1 and via intracerebral hemorrhage for COL4A1/2." (PMID 36300346, 2022). "For NOTCH3 and HTRA1, cardiovascular risk factors, as assessed by the FRS, increased ischemic stroke risk in variant carriers, and there was a statistical interaction between variant status and FRS." (PMID 36300346, 2022). "High-temperature requirement A serine peptidase 1 (HTRA1), of which genetically predicted lower plasma levels were associated with extensive HIP-PVSs, is encoded by a gene harboring both rare mutations causing monogenic cSVD28 and common variants associated with ischemic stroke and WMHs20,29,30." (PMID 41266628, 2025). "In contrast, genetic propensity to common ischemic stroke, as assessed by PRS, was only associated with increased risk in individuals without NOTCH3 or HTRA1 variants." (PMID 36300346, 2022).
dementia (8 papers, 2021 to 2025). Loss of intellectual abilities interfering with an individual's social and occupational functions. "NOTCH3 carriers had increased vascular dementia risk (OR, 5.42; 95% CI, 3.11-8.74), HTRA1 carriers an increased all-cause dementia risk (OR, 2.17; 95% CI, 1.28-3.41), and COL4A1/2 carriers an increased intracerebral hemorrhage risk (OR, 3.56; 95% CI, 1.34-7.53)." (PMID 36300346, 2022). "The DEG Htra1 (microglia, neurons, and astrocytes) formed connections with both dementia and cerebrovascular diseases." (PMID 39456952, 2024).
endometrial cancer (7 papers, 2012 to 2024). Primary or metastatic malignant neoplasm involving the endometrium (mucous membrane that lines the endometrial cavity). "In endometrial cancer cell lines, exogenous HTRA1 expression resulted in a decrease in the invasive and migration potential of these cells." (PMID 27809811, 2016). "Narkiewicz and colleagues studied HtrA1, HtrA2 and HtrA3 mRNA and protein by two semi-quantitative techniques, RT-PCR (mRNA) and WB (protein), in 124 women; 88 with endometrial cancer and 36 with normal endometrium." (PMID 26035313, 2015). "In particular, studies in ovarian and endometrial cancer reported reduced HTRA1 protein levels in 59% and 57% of the cases." (PMID 23580433, 2013). "Third, HtrA1 RNA and protein expression was decreased in human endometrial cancers vs. normal controls, with significant negative correlations between HtrA1 and TGFβ1 levels, and HtrA1 protein expression and endometrial cancer grade." (PMID 22761798, 2012). "Their results illustrated that HtrA1 mRNA levels in endometrial carcinoma were significantly lower than in the normal endometrium." (PMID 22935172, 2012). "A mouse model strongly supports these data as increased numbers of micrometastases could be found in the lung of mice after i.v. injection of endometrial cancer cells expressing HTRA1-siRNA." (PMID 23580433, 2013). "Additionally, as the endometrial cancer histological grade (G1, G2, G3) increased, there was clearly a greater decrease in HtrA1 mRNA levels." (PMID 22935172, 2012). "Accordingly, downregulation of HTRA1 expression has been reported for various cancer types such as ovarian and endometrial cancer compared to non-malignant tissue." (PMID 23580433, 2013).
hepatocellular carcinoma (7 papers, 2015 to 2024). A malignant tumor that arises from hepatocytes. "The emerging evidence has demonstrated that HtrA1 participates in the inhibition of cancer cell apoptosis, invasion and metastasis, and down-regulation of HtrA1 protein is associated with poor survival in mesothelioma, hepatocellular carcinoma and breast cancer." (PMID 31501409, 2019).
Polypoidal choroidal vasculopathy (7 papers, 2012 to 2025). The presence of aneurysmal 'polypoidal' lesions in the choroidal vasculature. "HTRA1-knockout mice also show no retinal changes at 12 months, though overexpression of HTRA1 has been linked to pathology in models of polypoidal choroidal vasculopathy and zebrafish photoreceptor degeneration." (PMID 41279129, 2025). "Multiple genetic studies have suggested that high-temperature requirement serine protease (HTRA1) is associated with polypoidal choroidal vasculopathy (PCV)." (PMID 23056244, 2012). "Overexpression of HTRA1 has been shown to induce polypoidal choroidal vasculopathy and wet AMD like phenotypes in mouse models (." (PMID 37174708, 2023). "Specifically, in a mouse model with RPE specific human HTRA1 overexpression, BrM EL damage, RPE atrophy, photoreceptor degeneration, and polypoidal choroidal vasculopathy (PCV) are reported by 11 months of age using electron microscopy." (PMID 37174708, 2023). "Consistent with the potential role of wound response in advanced AMD, experimentally induced HTRA1 expression in RPE results in altered Brüch’s membrane structure, polypoidal choroidal vasculopathy, and degeneration of the RPE and photoreceptors in mouse models." (PMID 26150894, 2015). "Our transgenic mouse overexpressing Htra1 through a ubiquitous CAG promoter (CAG-Htra1 Tg mouse) showed a CNV-like phenotype after 12 months while others have, using RPE-specific promoters, demonstrated a polypoidal choroidal vasculopathy (PCV)-like phenotype but not CNV." (PMID 33636181, 2021).
cerebrovascular disease (6 papers, 2017 to 2025). "Conversely, the effect of predicted damaging missense variants in HTRA1 and cerebrovascular disease was strengthened when R227W was excluded." (PMID 41190437, 2025). "To further explore the nature of the association between HTRA1 and vascular disease, we reviewed variant-level associations with our coronary artery disease and cerebrovascular disease phenotypes." (PMID 41190437, 2025). "The candidate gene heterozygous HTRA1 missense mutation was obtained by genetically screening the currently known genes and hereditary cerebrovascular disease related genes." (PMID 29561953, 2018). "Among these, HtrA1 is implicated in several cancers, and cerebrovascular disease." (PMID 29093542, 2017). "Therefore, the SNP of HTRA1 is considered not present in the normal population, but present in the family members who are either diagnosed with cerebrovascular disease or positive in clinical imaging." (PMID 29561953, 2018).
colorectal cancer (6 papers, 2015 to 2024). A primary or metastatic malignant neoplasm that affects the colon or rectum. "Note that silencing of the HTRA1 gene has been previously linked to colorectal cancer, in a yet unexplained mechanism, and to numerous cancerous phenotypes such as increased proliferation, DNA instability, and failure in DNA damage checking." (PMID 29269789, 2017). "Recently it has been shown that epigenetic silencing of the HTRA1 gene was linked to numerous cancerous phenotypes, and specifically to colorectal cancer." (PMID 29269789, 2017). "We found that the HTRA1 mRNA level was higher in colorectal cancer tissue as compared to the unchanged mucosa, specifically in primary lesions of metastasizing cancer." (PMID 32486357, 2020). "Eventually, 15 papers assessing HtrA1 expression at 10 tumours sites (stomach, liver, bladder, breast, esophagus, thyroid, endometrium, pleura, ovary, colorectum cancer) were included in the meta-analysis." (PMID 29409460, 2018). "The alterations in the HTRA1/2 genes’ expression are connected with metastatic potential of colorectal cancer and may affect patient survival." (PMID 32486357, 2020). "Colorectal cancer ranks first in incidence and second in mortality in Europe for both genders, yet, HtrA1 has never been investigated as a possible diagnostic and/or prognostic marker in this tumor." (PMID 26035313, 2015). "It would also be interesting to explore whether HtrA1 has a role in those tumors for which a screening test is available but has suboptimal sensitivity, such as colorectal cancer." (PMID 26035313, 2015). "However, studies on HTRA1 were mainly focused on its effect on tumor progression, the functional mechanism of of HTRA1 in colorectal cancer cells has not been clarified." (PMID 38740771, 2024).
lung carcinoma (6 papers, 2013 to 2023). "According to immunohistochemistry of human lung cancer specimens, the expression of HtrA1 is significantly downregulated in metastasis of primary tumors and lymph node, which means that it is possibly associated with the progression of lung cancer." (PMID 34563186, 2021). "In human nonsmall cell lung cancer (NSCLC), the targeting of HDAC/RXR/HtrA1 signaling axis may increase HtrA1 expression and overcome CDDP resistance." (PMID 34563186, 2021).
alopecia (5 papers, 2020 to 2026). Hair loss usually from the scalp. "In family 1, the same HTRA1 mutation was detected in the son of the proband, who experienced obvious alopecia and an acute lumbago attack at his thirties." (PMID 36035189, 2022). "Neither of the two patients in our study had apparent symptoms of alopecia or lumbago, which was consistent with previous findings, in which HTRA1-CSVD had a lower incidence of extra-neurological symptoms than classic CARASIL." (PMID 36619910, 2022).
amyloid (5 papers, 2013 to 2025). "Significantly, these peptides have been previously identified in amyloid deposits in vivo, supporting the idea that HtrA1 is a causative agent for TGFBIp-associated amyloidosis in corneal dystrophy." (PMID 31197037, 2019).
coronary artery disease (5 papers, 2023 to 2025). "Consistent with this, common noncoding variants in HTRA1, which likely affect vascular risk by changing vascular HTRA1 expression, increase the risk of both cerebrovascular and coronary artery disease." (PMID 41190437, 2025). "A study found that increased circulating HTRA1 levels are causally associated with a reduced risk of coronary artery disease." (PMID 40406620, 2025). "The association of coronary artery disease with predicted damaging variants in HTRA1 led us to consider whether disease of the coronary circulation might be an unrecognized feature of other monogenic cerebral small vessel disease syndromes." (PMID 41190437, 2025). "Increasing levels of circulating HTRA1 were causally associated with decreased risk of coronary artery disease in our PWMR, suggesting that HTRA1 may play a protective role in disease." (PMID 38989470, 2024). "Both SGTB and HTRA1 were downregulated in the aorta of patients with coronary artery disease compared with controls." (PMID 41190437, 2025). "Interestingly, HTRA1 expression was significantly downregulated in the aorta from patients with atherosclerotic coronary artery disease versus controls (false discovery rate–corrected P=3.4×10−4)." (PMID 41190437, 2025). "HTRA1 was identified as a potential therapeutic target for coronary artery disease." (PMID 40406620, 2025). "Therefore, we decided to focus on COL6A3 and HTRA1 as potential regulators of coronary artery disease in humans." (PMID 38989470, 2024). "Importantly, this model does not imply that damaging variants in HTRA1 cannot cause both clinically manifest cerebrovascular and coronary artery disease; variants that have no proteolytic capacity to any substrate or change expression of HTRA1 would be expected to alter the risk of both pathologies." (PMID 41190437, 2025).
Hypertension (5 papers, 2011 to 2024). The presence of chronic increased pressure in the systemic arterial system. "In the case–control study, weak correlations were observed between the methylation levels of a few CpG sites in the HTRA1 amplicons and hypertension, HDL-C, current smoking status, TC as well as TG levels." (PMID 36581876, 2022). "The mRNA level of HTRA1 in 72 IS cases and 72 hypertension controls were measured and compared." (PMID 33746601, 2021). "However, four meaningfully distinct clusters of patients were identified that were most strongly differentiated by their cardiovascular health status (histories of hypercholesterolemia and hypertension), and the alleles of ARMS2/HTRA1 rs1049331." (PMID 21682878, 2011). "However, Clusters 1 and 3 would represent a higher opportunity target sub-population of AMD patients, as they in total represent 50.2% of the neovascular AMD population, and tend to have high blood pressure in combination with a high likelihood of carrying the ARMS2/HTRA1 TT genotype." (PMID 21682878, 2011). "In addition, HTRA1-CSVD can be misdiagnosed as sporadic CSVD since aging and arterial hypertension are the contributing factors for both pathologies." (PMID 34946904, 2021).
scrub typhus (5 papers, 2018 to 2025). Scrub typhus is a rare dust mite-borne infectious disease caused by the Orientia tsutsugamushi bacterium and characterized clinically by an eruptive fever which is potentially serious. "Molecular mimicry may also play a role in the case of HTRA1-associated MN, in which bacterial form of the HTRA protein found in the cell wall of Orientia tsutsugamushi is known to be antigenic and has been used in a vaccine developed against scrub typhus, demonstrating immunogenicity." (PMID 34899763, 2021).
atherosclerosis (4 papers, 2018 to 2025). A disease characterized by the build-up of fatty material and calcium deposition in the arterial wall resulting in partial or complete occlusion of the arterial lumen. "Further in vivo studies are needed to clarify the mechanism by which HTRA1 may influence atherosclerosis." (PMID 38989470, 2024). "Several other module genes, including immediate neighbors of CAD candidate genes (e.g., CSNK2A1 and HTRA1) are also druggable and thus may be repurposed for modulating the effects of this module in the context of atherosclerosis prevention." (PMID 29467471, 2018). "The mechanism may involve increased HTRA1 expression in smooth muscle cells and endothelial cells, which inhibits TGF-beta signaling in atherosclerosis, thereby preventing neointima formation and pathological endothelial-mesenchymal transition." (PMID 40406620, 2025).